NAT10 (N-acetyltransferase 10)
Diseases named in the same sentence as NAT10 in open-access papers (continued):
Sharing a sentence is not in itself a finding about the gene and the disease.
cancer (continued). "To reinforce our findings, we crossed K14CreER mice with Nat10flox/flox mice to generate K14CreER; Nat10flox/flox (NAT10‐cKO) mice, which allowed us to conditionally delete Nat10 in K14+ cancer stem cells." (PMID 35522942, 2022). "Approximately 96% of the FA metabolic gene transcripts were enriched, suggesting that NAT10 regulates FA metabolism in palmitate‐loaded cancer cells in an ac4C‐dependent manner." (PMID 36149760, 2022). "Although NAT10‐mediated modification of ac4C peaks on RNA and proteins has been elucidated, knowledge about the role of ac4C on mRNA and its regulatory networks in cancer remains intricate to this day." (PMID 35522942, 2022). "Cancer suppression through the inhibition of N-acetyltransferase 10 (NAT10) by its specific inhibitor Remodelin has been demonstrated in a variety of human cancers." (PMID 35743017, 2022). "Using TIMER2 datasets, we calculated the coefficients of NAT10 expression and immune infiltration levels in 40 cancer types." (PMID 34094911, 2021). "In this study, we systematically analyzed the pan-cancer expression and correlations of NAT10, using databases including Oncomine, PrognoScan, GEPIA2, and Kaplan-Meier Plotter." (PMID 34094911, 2021). "In the current study, we systematically analyzed the pan-cancer expression of NAT10 and its correlations, using databases including Oncomine, PrognoScan, GEPIA2, and Kaplan-Meier Plotter." (PMID 34094911, 2021). "Here, we report that a higher level of NAT10 mRNA and protein was comprehensively found in multiple cancers according to several different databases." (PMID 34094911, 2021). "Compared with normal tissues, NAT10 showed higher expression in most cancers based on combined data from TCGA and GTEx." (PMID 34094911, 2021). "Using PrognoScan, we analyzed the role of NAT10 in each cancer type (number of cancer types = 12) and the relationships between NAT10 expression and prognosis in different cancers." (PMID 34094911, 2021). "NAT10, the only confirmed regulator of mRNA acetyltransferase, shows remarkable correlation with most cancers in immune infiltration." (PMID 34094911, 2021). "Distinct from the results of pan-cancer analysis of NAT10, our proposition demonstrates the difference between NAT10 and THUMPD1 in clinical and immunological function, though they both serve as the writing tools of ac4C." (PMID 34762107, 2021). "Although studies of NAT10 have been limited, increased levels of ac4C in urine are known to be correlated with four types of cancer." (PMID 34094911, 2021). "We also used the “Pathological Stage Plot” module in GEPIA2 to get the correlation between NAT10 expression and the pathological stages of cancers, including KIRP, LIHC, LUAD and PAAD (all p <0.05) but not others." (PMID 34094911, 2021). "Nine of the 33 cancer types showed significant relationships between NAT10 expression levels and OS, seven showed significant relationships with PFS, five with DFS, and seven with DSS." (PMID 34094911, 2021). "Second, although NAT10 plays an important part in ac4C formation in mRNA, there was no information in the databases about the detailed changes in ac4C in these cancers." (PMID 34094911, 2021). "Analysis of publically accessible information from the gene expression omnibus (GEO) database and the cancer genome atlas (TCGA) showed consistently elevated NAT10 expression in NSCLC tissues as well as in a variety of other cancer types, which is consistent with these findings." (PMID 41310903, 2025). "Knockdown NFE2L3 or LASP1 restored the changes in cell proliferation and migration caused by overexpression of NAT10, indicating that NAT10 might perform similar functions through NFE2L3/LASP1 signalling in other cancers." (PMID 40169553, 2025). "Additionally, interactions between NAT10 and other components of the TME, such as cancer‐associated fibroblasts, endothelial cells, and immunosuppressive cells, will be a research focus." (PMID 39764566, 2025).
cancer (continued). "Accumulating evidence has highlighted the significance of NAT10 in cancer biology, where it promotes tumor initiation, metastasis, and progression by catalyzing ac4C modifications on mRNA, thereby enhancing translational efficiency and driving the expression of oncogenic genes." (PMID 40109769, 2025). "Additionally, NAT10-mediated ac4C modification facilitates adaptive stress responses in cancer cells to drugs and other extracellular stimuli." (PMID 39905540, 2025). "NAT10-mediated ac4C modification promotes the progression of different cancers, including CRC." (PMID 40245789, 2025). "Since NAT10 is a well-established ac4C writer in promoting cancer progression, our study proposed that it may mechanistically regulate FOXD1 ac4C modification in NPC cells." (PMID 40999468, 2025). "Looking ahead, utilizing these cutting‐edge technologies for developing drugs targeting NAT10 and its RNA ac4C modification may offer more precise and personalized treatment options for cancer therapy, greatly improving clinical outcomes and patient prognoses." (PMID 39764566, 2025). "To investigate whether NAT10 exerted oncogenic roles in HCC, we first created HCC cell lines with NAT10 knockdown and assessed its effect on cancer cell phenotypes." (PMID 41476650, 2025). "In addition to Remodelin, several other NAT10 inhibitors have demonstrated significant potential in cancer treatment, highlighting their therapeutic relevance and possible clinical applications." (PMID 41310903, 2025). "Both NAT10 protein and mRNA levels were significantly increased in cancer cell lines." (PMID 41203621, 2025). "High NAT10 expression levels often predict poor cancer patient prognosis." (PMID 39817252, 2025). "NAT10 also harbors an RNA helicase domain, the function of which is obscure in cancer biology." (PMID 40138393, 2025). "Furthermore, they identify G‐749 as a potential NAT10 inhibitor to suppress cancer metastasis by impairing lysosomal acidification." (PMID 40729677, 2025). "Specifically, NAT10 may exert a stronger cancer-promoting effect in KRAS mutant cells compared to KRAS wild-type cells." (PMID 39905540, 2025). "This review not only summarizes the critical role of NAT10 in ac4C modification but also explores its potential impact on gene expression regulation, cellular functions, and its involvement in various diseases, such as cancer and neurodegenerative disorders." (PMID 39764566, 2025). "After DNA damage occurs or cancer develops, NAT10 can translocate." (PMID 39817252, 2025). "Collectively, NAT10 exhibits multifaceted, non-ac4C-dependent roles in regulating genome stability, DNA damage response, and chemoresistance through substrate-specific acetylation, positioning it as a context-dependent therapeutic target in cancer." (PMID 40588654, 2025). "In summary, inhibition of NAT10 via pharmacological means may be a promising strategy for the treatment of cancers." (PMID 41316475, 2025). "Multiple studies suggest that ncRNAs can interact with NAT10, further impacting cancer development." (PMID 40881352, 2025). "Thus, NAT10 acts as a master molecular switch for the metastatic cascade, coordinating the distant colonization of cancer." (PMID 41316475, 2025). "Studies have shown that NAT10‐mediated ac4C acetylation is highly expressed in various cancers, promoting cancer cell proliferation, invasion, and metastasis by regulating metabolic pathways, enhancing stress response, and affecting genes related to the cell cycle and apoptosis." (PMID 39764566, 2025). "•The levels of ac4C and NAT10 were increased in cancer tissues and RB cell lines." (PMID 40344913, 2025).
cancer (continued). "Additionally, NAT10 promotes PD-L1 transcription in various cancers by facilitating NPM1 acetylation, which correlates with poor patient prognosis." (PMID 40109769, 2025). "Therefore, there is an urgent need to identify effective small‐molecule drugs targeting NAT10 and to explore their therapeutic potential in cancer treatment." (PMID 41476650, 2025). "As a new drug resistance driver, NAT10 is an important target for cancer therapy." (PMID 41316475, 2025). "Consequently, NAT10-mediated enhancement of DNA repair pathways safeguards genomic integrity in cancer cells." (PMID 41316475, 2025). "NAT10, a multifunctional enzyme, has been recognized as a crucial factor in the complex landscape of cancer biology, with its diverse role in tumorigenesis affecting processes such as cell proliferation, differentiation, survival, and genomic stability maintenance." (PMID 40288646, 2025). "NAT10 biological functions are often involved in the occurrence and progression of cancer." (PMID 39817252, 2025). "Therefore, further studies are required to validate additional mechanisms and clarify the role of NAT10 in different cancer types." (PMID 39817252, 2025). "However, subsequent studies unexpectedly found that overexpressing NAT10 shortened telomere length, which is generally unfavorable for cancer cells." (PMID 39817252, 2025). "Additionally, NAT10 promotes cytoskeletal remodeling and cell motility, key aspects of cancer metastasis, by regulating genes involved in cytoskeletal dynamics." (PMID 39764566, 2025). "We also review the mechanisms by which NAT10 plays roles in various cancer types." (PMID 39817252, 2025). "Notably, analyses of transcriptomic and metabolomic sequencing results from HB cells with NAT10 knockdown indicated that NAT10 was crucial for the PPP in cancer cells." (PMID 40303290, 2025). "NAT10 also plays a pivotal role in cancer immune regulation." (PMID 40109769, 2025). "Thus, there is a need to employ NAT10 knockout mouse models and develop more precise and accessible methods for detecting ac4C modifications in cancer, thereby enhancing the reliability and accuracy of these findings." (PMID 39640362, 2024). "N-acetyltransferase 10 (NAT10) has been identified as a cancer-promoting factor." (PMID 38243170, 2024). "Notably, NAT10 is highly expressed in a variety of cancers, including colon, liver, lung and acute myeloid leukemia." (PMID 38308713, 2024). "Furthermore, recent studies on ac4C in cancer were performed on cancer cell lines or patient‐derived organoids, where NAT10 is knocked down or overexpressed for in vitro validation." (PMID 39640362, 2024). "Notably, NAT10 has been identified as a promoter of cancer metastasis and epithelial-mesenchymal transition (EMT) through ac4C modification of COL5A1 mRNA." (PMID 39418179, 2024). "Pri-miRNA ac4C catalyzed by NAT10 exerted its biological function in clinical cancers." (PMID 38308713, 2024). "Remarkably, NAT10 depletion and gefitinib therapy synergistically inhibit cancer cell invasion and migration, showing that this approach alleviates gefitinib resistance and provides novel insights for developing effective cancer treatment strategies." (PMID 38233930, 2024). "Targeting NAT10 has shown significant suppressive effects in various cancers." (PMID 39640362, 2024). "Besides, NAT10 can regulate the signaling pathways in cancer, which influences proliferation, migration, and apoptosis of cancer cells." (PMID 39640362, 2024). "At present, NAT10 is mainly focused on cancer-related research." (PMID 39251905, 2024). "Moreover, our study shows that NAT10 functions as a cancer-promoting molecule by targeting the glycolysis genes PFKM and LDHA directly or indirectly through acetylation in mRNA to reduce glycolysis breakdown and inhibit tumorigenesis." (PMID 38233839, 2024). "There are presently conflicting reports as to whether NAT10 functions primarily as a promoter or suppressor of cancer." (PMID 38182571, 2024).
cancer (continued). "Research investigating the role of NAT10 in cancer typically adopts two primary approaches." (PMID 39640362, 2024). "This study suggests that the NAT10/NPM1 axis is a promising therapeutic target in malignant tumors." (PMID 38243170, 2024). "Moreover, Mahmood Hassan Dalhat demonstrates that in NAT10-depleted cancer cells, the expression of essential genes such as SLC7A11, which are associated with ferroptosis, are significantly downregulated." (PMID 39251905, 2024). "In CC, HOXC8 binds to the promoter region of NAT10, upregulating its expression in cancer tissues." (PMID 39640362, 2024). "Moreover, we observed that 1.73% prevalence of NAT10 mutations (9/517) in LUAD, 1.23% (6/485) in LUSC and 1.35% (138/10156) in all cancer types, respectively." (PMID 38308713, 2024). "Moreover, NAT10 is highly expressed in various clinical cancers and negatively correlated with poor prognosis." (PMID 38308713, 2024). "Importantly, this regulatory mechanism establishes a basis for combination therapy with anti-CTLA-4 antibodies and NAT10 inhibitors in cancer." (PMID 38243170, 2024). "NAT10 inhibition is a mechanistically unique strategy that may have the potential to overcome cancer drug resistance." (PMID 39246323, 2024). "One approach considers NAT10 as an oncogene, examining its involvement in cancer progression." (PMID 39640362, 2024). "NAT10 mediates the formation of micronuclei (MN) by enhancing DNA replication in cancer cells." (PMID 37237981, 2023). "Recently, we reported that NAT10 regulates fatty acid metabolism in cancer cells." (PMID 37237981, 2023). "Previously, we discovered that Remodelin, the only known small molecule inhibitor of NAT10, alters lipid metabolic pathways in cancer cells, which include fatty acid elongation in mitochondria, fatty acid metabolism, and mitochondrial beta-oxidation of saturated fatty acids." (PMID 37237981, 2023). "Since we found ferroptosis among the top pathways in NAT10 KD cancer cells, we wanted to explore whether NAT10 depletion induces ferroptosis." (PMID 37237981, 2023). "Additionally, a decrease in the cell viability (1 day < 2 day < 3 day) of all three cell lines was noticed in NAT10-depleted cancer cells, suggesting NAT10 is crucial for cancer growth." (PMID 37237981, 2023). "In conclusion, our study has unveiled evidence that targeting NAT10 in cancer induces ferroptosis, and we propose that this mechanism could be explored for possible therapeutic and cancer treatments." (PMID 37237981, 2023). "Albeit current findings dictate crucial role of NAT10 in cell apoptosis, proliferation, and motility, thus modulating cancer progression, metabolism and aging, whether NAT10 regulates cutaneous wound healing and skin barrier maintaining is largely unknown." (PMID 37644005, 2023). "Moreover, increased NAT10 expression was positively correlated with increased Ki‐67 expression (P<0.05), which is a marker for cancer cell proliferation and poor prognosis." (PMID 37818745, 2023). "The effect of NAT10 on LN metastasis was measured by in vivo bioluminescence imaging, and the popliteal lymph nodes that represented the first and rate-limiting steps of cancer metastasis were examined after 4 weeks." (PMID 37914704, 2023). "Finally, our results suggest that ferroptosis is induced in both NAT10-depleted and Remodelin-treated cancer cells at different stages of the SLC7A11/GSH/PLOOH axis." (PMID 37237981, 2023). "Recent studies have shown that deregulation of NAT10 may be involved in the pathogenesis of several types of human cancer." (PMID 36609449, 2023). "In the current work, we explore the possibility of whether NAT10 acts as an epitranscriptomic regulator of the ferroptosis pathway in cancer cells." (PMID 37237981, 2023). "NAT10 is the only confirmed regulator of mRNA acetylation and has multiple functions in cancer." (PMID 36908042, 2023).
cancer (continued). "Additionally, the C11 BODIPY assay showed a remarkable decrease in fer-1-treated NAT10-depleted cancer cells, suggesting reduction in lipid ROS levels." (PMID 37237981, 2023). "Here, we found that NAT10 depletion implicates reducing the lipid levels, which could be why morphological changes, reduced cell proliferation and growth were observed in NAT10 depleted cancer cells." (PMID 36149760, 2022). "Therefore, the reduced peak intensity of acetyl‐CoA is consistent with decreased global ac4C level in NAT10 depleted cancer cells, which was measured via dotblot." (PMID 36149760, 2022). "Therefore, targeting NAT10‐mediated ac4C modification in cancer shows promising therapeutic benefits." (PMID 36149760, 2022). "Therefore, in this study, we explored the impact of NAT10 depletion in cancer cells using unbiased RNA‐seq." (PMID 36149760, 2022). "Even though it has been suggested that NAT10 is involved in ribosome biogenesis, aging syndrome, DNA damage, and cancers, studies on the mechanism by which it modulates ac4C modification in cancer development, especially CRC, are limited." (PMID 36522719, 2022). "Thus, our study provides for the first time the crucial role of NAT10‐dependent ac4C modification in regulating FA metabolism and lipid accumulation in cancer cells." (PMID 36149760, 2022). "In addition, NAT10 participates in mitotic cytokinesis and the cell stress response, and it is thus usually highly expressed in a variety of human cancers." (PMID 35743017, 2022). "Furthermore, the pan-cancer expression of NAT10 was examined based on RNA sequencing data from TCGA using TIMER2." (PMID 34094911, 2021). "Several evidences have pointed to the role of NAT10 in cell proliferation, cell migration, DNA damage response, and EMT suggests that NAT10 could be a suitable therapeutic target for cancer treatment." (PMID 33723305, 2021). "Then, the mRNA expression levels of NAT10 were analyzed in Oncomine over a cancer-wide range." (PMID 34094911, 2021). "In summary, increased NAT10 expression was correlated with poor prognosis in 12 types of cancer, especially ACC, KIRP, LIHC, HNSC, and PCPG, and with increased immune infiltration levels of CD8+ T cells, CD4+ T cells, macrophages, neutrophils, and DCs in various cancers." (PMID 34094911, 2021). "Increasing evidence indicated that NAT10 might be a potential therapeutic target for cancer treatment." (PMID 34362389, 2021). "High NAT10 expression in cancer cells increases the expression of the oncogenes." (PMID 33425753, 2020). "Thus, functional studies of NAT10 will be helpful for the further study of the development and occurrence of cancer." (PMID 28859621, 2017). "Recent evidences indicate that NAT10 is involved in the development of human cancers." (PMID 28859621, 2017). "In addition, NAT10 has been reported to play a significant role in cancer drug resistance." (PMID 39764566, 2025). "Using AlphaFold2 to predict the NAT10 protein structure with high confidence, followed by molecular docking simulations via the AutoDock algorithm, we screened a library of over 4300 anti‐cancer small molecules from MCE to calculate their binding affinities with NAT10." (PMID 41476650, 2025). "Additionally, exploring the interplay between NAT10 and other epigenetic modifications, such as histone modifications and m6A methylation, will provide a more comprehensive understanding of ac4C acetylation in cancer biology." (PMID 41203621, 2025). "We next investigated whether ATP6V0E1 mediates the effect of NAT10 on cancer metastasis." (PMID 40729677, 2025). "Consequently, the cancer-promoting effect of NAT10 in KRAS wild-type cells is relatively weak." (PMID 39905540, 2025). "Furthermore, NAT10 has shown promise as an early detection marker for cancer." (PMID 41316475, 2025). "Additionally, the mRNA expression of NAT10 was increased in cancer tissues." (PMID 40344913, 2025).